BRCA1 (BRCA1 DNA repair associated)
Diseases named in the same sentence as BRCA1 in open-access papers (continued):
Sharing a sentence is not in itself a finding about the gene and the disease.
breast cancer (continued). "The seminal cloning of the breast susceptibility gene 1 (BRCA1) in 1994 heralded a significant advancement in the early diagnosis and understanding of breast cancer biology." (PMID 37762577, 2023). "In a pooled analysis, the risk for breast cancer before the age of 40 years in carriers of BRCA1/2 germline mutations was 9.4% to 12%." (PMID 36980802, 2023). "It has been suggested that RRSO at premenopausal age also reduces the risk of breast cancer in BRCA1/2 GPV carriers by up to 50%." (PMID 37046756, 2023). "RRSO is typically recommended for patients aged between 35 and 40 years and upon completion of childbearing for breast cancer patients with BRCA1 pathological variants, and between 40 and 45 years for BRCA2 pathological variants." (PMID 36849964, 2023). "In order to identify those with a higher hereditary propensity to breast cancer, AI can analyze genetic data, such as breast cancer gene 1 (BRCA1) and BRCA2 mutations." (PMID 38192969, 2023). "BRCA1 is a gene associated with breast cancer that is involved in biological processes such as DNA repair and gene expression regulation." (PMID 37759912, 2023). "Women who carry pathogenic BRCA1 variants are particularly likely to develop breast cancer (BC) and ovarian cancer (OC), with a 45–79 percent and 39–48 percent chance, respectively." (PMID 37958491, 2023). "In breast cancer, the hypermethylation of the BRCA1 promoter has been associated with decreased BRCA1 expression and sensitivity to DNA‐damaging drugs and PARP inhibitors." (PMID 37229486, 2023). "According to another research, breastfeeding can diminish the risk of some types of BC, such as BRCA1-associated breast cancer (e.g., BLBCs), among women who have had two or more years of lactation." (PMID 38046902, 2023). "The cumulative lifetime risk up to age 80 to develop breast cancer is 72% for BRCA1 GPV (95% CI: 65–79%) and 69% for BRCA2 GPV (95% CI: 61–77%)." (PMID 37046756, 2023). "One of these high-risk pedigrees included five related, sampled, recurrent breast cancer cases that had previously been identified to carry the pathogenic BRCA1 Q1313X variant." (PMID 38136396, 2023). "BRCA1 was found to be linked with an elevated risk across all subtypes in breast cancer, although the odds ratios (ORs) exhibited significant variation, with the highest OR observed in triple-negative disease (OR, 55.32; 95% CI, 40.51-75.55)." (PMID 37781206, 2023). "The patient had a family history of cancer (grandmother with pancreatic cancer, mother with breast cancer) and a germline BRCA1 mutation was identified." (PMID 38260832, 2023). "Our findings provide preliminary evidence of an inverse association between both exposures and the risk of breast cancer, particularly among BRCA1 mutation carriers." (PMID 37345127, 2023). "BRCA1/2 are well known hereditary breast cancer predisposition genes and have been extensively studied." (PMID 38017116, 2023). "The first randomized phase III OlympiAD clinical trial tested a PARP inhibitor, olaparib for breast cancer patients harboring an inherited BRCA1/2 mutation." (PMID 36631481, 2023). "Women with hereditary breast and ovarian cancer syndrome have an increased risk of developing cancer, mainly breast cancer (BC)—absolute risk > 60% for BRCA1/2 carriers—and ovarian cancer (OC)—absolute risk of 39–58% for BRCA1 and 13–29% for BRCA2 carriers." (PMID 37754482, 2023). "The downregulation of Emi1 in BRCA1-deficient breast cancer cells induces primary and acquired resistance to PARPi both in vitro and in vivo." (PMID 38041032, 2023). "EMBARCA was the phase III randomized clinical trial that compared the PFS of talazoparib versus physician’s choice treatment in advanced breast cancer with germline BRCA1/2 mutations." (PMID 36673082, 2023).
breast cancer (continued). "Paradoxically, some studies also showed that RNF168 deletion led to the accumulation of R-loop in breast cancer and ovarian cancer cells with BRCA1/2 mutation, and the accumulation of R-loop leads to DSB, senescence and subsequent cell death." (PMID 36771081, 2023). "Women who inherit a BRCA1 or BRCA2 mutation have a substantial risk of developing breast cancer, which is estimated to be 72% and 69%, respectively." (PMID 37138170, 2023). "The National Comprehensive Cancer Network (NCCN) guidelines recommend detecting BRCA1/2 gene mutation for breast cancer patients of any type, which can guide the use of PARP inhibitors." (PMID 37114130, 2023). "For the 21 women who met synchronous bilateral breast cancer criterion only, three (14.3%) had a pathogenic variant (one in each BRCA1, PALB2, and RECQL)." (PMID 36544278, 2023). "Results displayed that the cumulative risk of breast cancer by age 80 is 72% for BRCA1 carriers and 69% for BRCA2 carriers." (PMID 37476378, 2023). "Men with BRCA1 variants have a lifetime breast cancer risk of 1–5%, 2–3% of pancreatic cancer, and 7–26% risk of PC." (PMID 37347260, 2023). "Constitutional methylation of BRCA1 detectable in blood cells was first associated with an increased risk of breast cancer tumors with features resembling BRCA1-mutated tumors over a decade ago3." (PMID 37752189, 2023). "In cancer cells with mutations in, for example, the breast cancer predisposition gene BRCA1, which is known to code for a protein involved in DNA repair, a significant portion of the RNA–DNA hybrids exit the nucleus and accumulate in the cytoplasm." (PMID 36902456, 2023). "Our screening efforts identified two truncating germline mutations in the gene encoding the BRCA1 complex partner ABRAXAS1 in German early-onset breast cancer patients." (PMID 37198153, 2023). "Several studies have found that the cumulative risk of developing breast cancer by 70 years of age is 55–72% in women with BRCA1 mutations and 45–69% in women with BRCA2 mutations, whereas the cumulative risk of breast cancer in the general population is 12%." (PMID 37957733, 2023). "Often, high-grade breast cancer and TNBCs show somatic mutations or abnormal BRCA1/BRCA2 expression." (PMID 37761830, 2023). "Germline pathogenic mutations in breast cancer predisposition genes were identified in four patients (BRCA1, n = 2; BRCA2, n = 2)." (PMID 36879128, 2023). "Following genetic diagnosis, this population of 187 women with BRCA1/2 P/LP variants was faced with the need to choose the preventive option for breast cancer, with 50 (26.7%) women choosing RRM and 137 (73.3%) women opting for IBS." (PMID 36971799, 2023). "We performed whole-genome sequencing on matched tumour and normal samples from high-risk non-BRCA1/BRCA2 breast cancer families to understand the germline and somatic mutational landscape and mutational signatures." (PMID 37316882, 2023). "Conversely, BRCA-1 gene mutation or silencing abolishes this inhibitory effect, enabling Fox A1 hypermethylation, fostering breast cancer." (PMID 37746260, 2023). "An algorithm integrating the mutation signatures in HRR that can both identify BRCA1/2 germline and sporadic-mutation-associated breast cancer has been advanced." (PMID 37173992, 2023). "BRCA1 encodes the breast cancer type 1 susceptibility protein, a regulator of DNA repair and the G2/M cell cycle checkpoint, the mutation of which leads to reduced expression, loss of function, and accelerated breast cancer progression." (PMID 38028209, 2023). "For example, RAD51 recombinase (RAD51) and Breast cancer type 1 (BRCA1), genes involved in double-stranded break homologous recombination, are linked to the development of ovarian and breast cancers and are also downregulated in uterine fibroids." (PMID 37107181, 2023).
breast cancer (continued). "Whereas, a greater rate of BRCA1/2 germline variants was reported in familial breast cancer patients from Lebanon (15.5%), and Egypt (19.8% for BRCA1 and 30.6% for BRCA2)." (PMID 37656691, 2023). "We extended these results by analyzing mutation data for human tumors and found BRCA1/2-deficient breast cancers display three- to fourfold more APOBEC-induced mutations." (PMID 37532520, 2023). "The P/LP variants most frequently associated with early onset hereditary breast cancer are those affecting the BRCA1 and BRCA2 (BRCA1/2) genes." (PMID 36971799, 2023). "Several studies have examined the potential risk modification of SNP/SNVs in familial breast cancers and, in particular, BRCA1, BRAC2, CHEK2, PALB2 and ATM mutation carriers." (PMID 36831687, 2023). "First, the low incidence of BRCA1/2 mutations in breast cancer leads to limited access to PARPis; second, breast cancer cells, particularly TNBC cells, have been observed to rapidly develop resistance to PARPis through multiple pathways after treatment." (PMID 37156759, 2023). "In one systematic review that included 3,807 patients in 23 observational studies, differences in outcomes between mastectomy and BCS among breast cancer patients with BRCA1/2 variants were analyzed." (PMID 37781190, 2023). "We chose 2 organoid lines from this biobank, 74T and 86T, which represent a luminal and a basal-like breast cancer line with low and high level of a BRCA1-deficiency signature (i.e., signature 3), respectively." (PMID 37943878, 2023). "Hereditary breast and ovarian cancer (HBOC) is a syndrome of predisposition to cancer development, including breast cancer and ovarian cancers, caused by germline pathogenic variants of BRCA1 or BRCA2 (gBRCA1/2-positive)." (PMID 37957733, 2023). "Germline mutations in BRCA1/2 account for 10–15% of ovarian cancers, 5–10% of breast cancers, and 3–5% of pancreatic and prostate cancers." (PMID 37291133, 2023). "The chr19p13.1 locus was originally identified as a breast cancer risk region in BRCA1 mutation carriers and TNBC patients." (PMID 36859531, 2023). "This study revealed a significant reduction in the frequency of p63+TCF7+ myoepithelial cells in normal breast tissues of BRCA1 mutation carriers, possibly contributing to their heightened breast cancer risk." (PMID 37762577, 2023). "This trial led to the approval of olaparib as a maintenance therapy for BRCA1/2 mutated breast cancers." (PMID 37035242, 2023). "In patients at high risk for breast cancer, such as BRCA1/2 mutations, prophylactic mastectomy is indicated, heavily reducing though not completely eradicating the risk of cancer." (PMID 36376583, 2023). "Since the approval of poly-adenosine diphosphate ribose polymerase inhibitors (PARPi) in BRCA1/2 mutant breast cancer in 2018, it has served as a risk-reducing medication and prolonged the prognosis-free survival distinctly." (PMID 37476378, 2023). "The primary genes associated with hereditary breast cancer are BReast CAncer gene 1 (BRCA1) and BRCA2, which produce proteins involved in DNA damage repair." (PMID 37181043, 2023). "Another study also demonstrated that germline BRCA1/2 mutations can increase the risk of developing contralateral breast cancer." (PMID 37293877, 2023). "The loss of function of the BRCA1 tumor suppressor is common in breast cancer, but experimentally, the BRCA1 inactivation promotes cell senescence." (PMID 37627161, 2023). "The model-predicted risk for developing breast cancer until the age of 70 years was 68%, and thus comparable to observed data for BRCA-1/2 mutation carriers provided by the literature ranging between 57% and 84%." (PMID 37365514, 2023). "Randomized controlled trials (RCTs) using PARP inhibitors or platinum for treating patients with metastatic, locally advanced, or recurrent breast cancer carrying BRCA1/2 pathogenic variants have shown efficacy, as evidenced by improved survival duration." (PMID 36865806, 2023).
breast cancer (continued). "Regarding tumor subtypes, BRCA1 breast cancers were associated with a TN subtype, whereas BRCA2 breast cancers were associated with a luminal subtype." (PMID 36905492, 2023). "We found that 14.7% (21/143) of breast cancer patients and 20.7% (79/382) of ovarian cancer patients were carriers of P/LP variants in BRCA1/2." (PMID 37664050, 2023). "For example, naturally occurring nonsense mutations in the tumor suppressor gene BRCA1 are associated with an increased risk of breast cancer." (PMID 37047074, 2023). "A breast cancer susceptibility gene 1 (BRCA-1) detection system based on an ultrasensitive cfDNA electrochemical biosensor called tetrahedral DNA framework (TDF)-modified gold nanoparticles (AuNPs) was reported." (PMID 36832253, 2023). "HR estimates for young-adult BMI (continuous measure) were less than 1 for premenopausal breast cancer risk in both BRCA1 and BRCA2 variant carriers, although the associations were not statistically significant." (PMID 37340476, 2023). "Our latest pick-up rates on patients with bilateral breast cancers with unselected age and family history were 21%, 16% from BRCA1/2 mutations, and 19% from 6 high-penetrance genes (data from out rountine lab)." (PMID 37174101, 2023). "More recently, PARP inhibitors were also tried in the setting of high-risk early-stage breast cancer with germline pathogenic BRCA1/2 variants (Olympia trial)." (PMID 37781190, 2023). "Germline mutations in BRCA1 are the most researched genetic lesion that increase the risk of breast cancer, but are present in only up to 5% of total breast cancer cases in Poland2." (PMID 37752189, 2023). "The survival benefit of PARP1 inhibitor in BRCA1-deficient breast cancer proved that the DNA repair pathway is a promising target for cancer treatment." (PMID 37968256, 2023). "Higher BMI and weight gain in adult life were risk factors for postmenopausal breast cancer in BRCA1 variant carriers." (PMID 37340476, 2023). "The randomized phase III trial, EMBRACA, compared another PARP inhibitor, Talazoparib, with single-agent CT in patients with advanced breast cancer with BRCA1/2 mutations." (PMID 37664050, 2023). "It has been reported that breast cancer patients with BRCA1 mutation was mostly found in triple-negative breast cancer." (PMID 36906594, 2023). "Women with a pathogenic BRCA1 or BRCA2 variant had an increased risk of breast cancer that was higher in those with a first-degree family history (relative hazard 10.3 and 7.8, respectively) than those without (7.2 and 4.7)." (PMID 37936660, 2023). "TNBC accounts for 15–20% of all breast cancer cases and is more frequently diagnosed in premenopausal young women and those carrying BRCA1 gene mutations." (PMID 37047393, 2023). "For women of the high-risk population, the cumulative risk of developing breast cancer by age 80 is 72% for BRCA1 and 69% for BRCA2 carriers." (PMID 36765786, 2023). "The NHS Grampian genetics team observed the BRCA1 missense variant, c.5207T > C; p.Val1736Ala, in a number of ovarian and breast cancer cases from Orkney." (PMID 36927983, 2023). "Of the 64 patients with a pathological variant of BRCA1/2, 38 patients were diagnosed with breast cancer." (PMID 37623237, 2023). "The prevalence of BRCA1 or BRCA2 germline pathogenic mutations is approximately 5% in patients with breast cancer." (PMID 37173992, 2023).
breast cancer (continued). "Currently, at-risk women are often identified through familial history of breast cancer, or genetic markers, such as BRCA1 or BRCA2 mutations, which cause approximately 60% of hereditary breast cancer." (PMID 37018164, 2023). "To identify genes whose deficiency confers drug resistance to the PARPi olaparib, we performed a genome-wide CRISPR genetic screen in MDA-MB-436 cells, a human breast cancer line harboring a BRCA1 mutation and which is sensitive to PARPi15." (PMID 37066268, 2023). "The setting is unique as 85% of all breast cancer patients diagnosed during the study period had been tested for the virtually single pathogenic BRCA1/2 mutation in the population." (PMID 38036573, 2023). "Knowing the BRCA1 and BRCA2 (BRCA1/2) gene mutation status can improve breast cancer patients’ health outcomes by guiding targeted treatment towards preventing breast cancer recurrence and other BRCA-related cancers." (PMID 36834079, 2023). "Protein-truncating variants in BRCA2 and ATM were associated with a high risk of breast cancer, whereas PTVs in BRCA1 and PALB2 were associated with a high risk of estrogen receptor (ER)-negative disease." (PMID 37790698, 2023). "Female BRCA1/BRCA2 (=BRCA) pathogenic variants (PVs) carriers are at a substantially higher risk for developing breast cancer (BC) compared with the average risk population." (PMID 37370730, 2023). "One percent of breast cancer present with sporadic mutations in BRCA1 with the promoter region in the gene being hyper-methylated in 11%–14% of cases thus inactivating the gene." (PMID 37662839, 2023). "Deeper understanding of breast cancer family history based on genetics led to the discovery of the first major susceptibility genes for breast cancer (BRCA1 and BRCA2) over 20 years ago." (PMID 36749458, 2023). "Talazoparib has shown a significant enhancement of progression-free survival in patients with advanced breast cancer with germline BRCA1/2 mutations as demonstrated by the EMBRACA clinical study." (PMID 36869202, 2023). "Previously, 3q29 region was shown as an amplified region in basal-like breast cancer with BRCA1 mutation, and it was also identified as a significantly altered region in the metastatic breast cancer cohort." (PMID 37190123, 2023). "The most frequent variants for breast cancer were in BRCA1 (deletion (ex 9–12) and c.115T > A (p.Cys39Ser)) and MUTYH c.118G > A (p.Gly396Asp); these variants were found in four patients each." (PMID 36833268, 2023). "For over two decades, genetic testing for women with an increased risk of breast cancer due to germline BRCA1 and BRCA2 mutations (gBRCAm) has allowed for better treatment planning, intervention, and long-term survival." (PMID 37623478, 2023). "The prevalence of BRCA1/2 mutations is higher in Indian breast and/or ovarian cancer patients, and delays in the diagnosis and treatment of breast cancer are associated with poor referral systems." (PMID 37886170, 2023). "We undertook this network meta-analysis to assess the efficacy and safety of pharmacotherapies for patients with metastatic, locally advanced, or recurrent breast cancer carrying BRCA1/2 pathogenic variants." (PMID 36865806, 2023). "In contrast, higher baseline BMI was associated with an increased risk for postmenopausal breast cancer for BRCA1 variant carriers (HR per 5 kg/m2 increase 1.20, 95% CI 1.02–1.42)." (PMID 37340476, 2023). "The enzyme, poly(adenosine diphosphate-ribose) polymerase (PARP) crucially controls this pathway, making PARP inhibitors a promising treatment strategy for patients with breast cancer carrying BRCA1/2 pathogenic variants." (PMID 36865806, 2023).